WNK4 (WNK lysine deficient protein kinase 4)
Description:
Serine/threonine-protein kinase component of the WNK4-SPAK/OSR1 kinase cascade, which acts as a key regulator of ion transport in the distal nephron and blood pressure (By similarity). The WNK4-SPAK/OSR1 kinase cascade is composed of WNK4, which mediates phosphorylation and activation of downstream kinases OXSR1/OSR1 and STK39/SPAK. Following activation, OXSR1/OSR1 and STK39/SPAK catalyze phosphorylation of ion cotransporters, such as SLC12A1/NKCC2, SLC12A2/NKCC1, SLC12A3/NCC, SLC12A5/KCC2 or SLC12A6/KCC3, regulating their activity. Acts as a molecular switch that regulates the balance between renal salt reabsorption and K(+) secretion by modulating the activities of renal transporters and channels, including the Na-Cl cotransporter SLC12A3/NCC and the K(+) channel, KCNJ1/ROMK (By similarity). Regulates NaCl reabsorption in the distal nephron by activating the thiazide-sensitive Na-Cl cotransporter SLC12A3/NCC in distal convoluted tubule cells of kidney: activates SLC12A3/NCC in a OXSR1/OSR1- and STK39/SPAK-dependent process (By similarity). Also acts as a scaffold protein independently of its protein kinase activity: negatively regulates cell membrane localization of various transporters and channels (CFTR, KCNJ1/ROMK, SLC4A4, SLC26A9 and TRPV4) by clathrin-dependent endocytosis (By similarity). Also inhibits the activity of the epithelial Na(+) channel (ENaC) SCNN1A, SCNN1B, SCNN1D in a inase-independent mechanism (By similarity). May also phosphorylate NEDD4L.
Synonyms: PRKWNK4; PHA2B
Tractability: Small molecule: a high-quality ligand is known; it belongs to a druggable protein family. PROTAC: UniProt records ubiquitination sites on it; ubiquitination databases record sites on it.
Target class: Kinase; Enzyme; Protein Kinase; Other protein kinase Wnk family; Other protein kinase group
Gene: Protein-coding gene on chromosome 17 (42,780,610 to 42,797,066, forward strand). Ensembl gene ENSG00000126562.
Subcellular location: Cell junction, tight junction
Pathways (Reactome):
Transport of small molecules: Stimuli-sensing channels
Gene Ontology:
Molecular function: protein binding; protein serine/threonine kinase activity; ATP binding; ion channel inhibitor activity; protein serine kinase activity; chloride ion binding; protein kinase activity
Biological process: distal tubule morphogenesis; monoatomic ion homeostasis; renal sodium ion absorption; intracellular signal transduction; negative regulation of protein localization to plasma membrane; negative regulation of sodium ion transport; protein phosphorylation; renal sodium ion transport; signal transduction; aldosterone secretion; calcium ion homeostasis; cellular response to xenobiotic stimulus; ERK1 and ERK2 cascade; gene expression; homeostatic process; inflammatory response; intracellular chloride ion homeostasis; macrophage activation; potassium ion transmembrane transport; regulation of blood pressure; regulation of potassium ion export across plasma membrane; response to aldosterone; response to dietary excess; response to xenobiotic stimulus; sodium ion transmembrane transport
Cellular component: bicellular tight junction; cytosol; membrane; cell body; cytoplasm
Genetic constraint (gnomAD): Loss-of-function variants: 94 observed, 120.04 expected, observed/expected ratio (o/e) 0.78, 90% interval 0.66 to 0.93. The upper end of that interval is the gene's LOEUF score, 0.93, which puts it in group 3 of 6, group 1 being the genes least tolerant of losing a copy. Missense variants: 1,542 observed, 1,697.8 expected, observed/expected ratio (o/e) 0.91, 90% interval 0.87 to 0.95. Synonymous variants: 655 observed, 698.42 expected, observed/expected ratio (o/e) 0.94, 90% interval 0.88 to 1.
Homologues: Orthologues: macaque WNK4 (97% identical), chimpanzee WNK4 (95% identical), dog WNK4 (89% identical), pig WNK4 (87% identical), mouse Wnk4 (86% identical), rabbit WNK4 (86% identical), rat Wnk4 (86% identical), guinea pig WNK4 (73% identical), zebrafish wnk4b (48% identical), Caenorhabditis elegans wnk-1 (29% identical), Drosophila melanogaster Wnk (28% identical), tropical clawed frog wnk4 (21% identical), and 2 more. Paralogues in human: WNK1 (40% identical), WNK2 (38% identical), WNK3 (34% identical), NRBP1 (11% identical), NRBP2 (11% identical), DSTYK (10% identical).
Diseases named in the same sentence as WNK4 in open-access papers:
WNK4 is named in the same sentence as 45 diseases in open-access papers, as found by Europe PMC text mining. Sharing a sentence is not in itself a finding about the gene and the disease. The quoted sentences say what the papers report.
Hypertension (42 papers, 2011 to 2025). The presence of chronic increased pressure in the systemic arterial system. "In particular, the decrease in Prdx5 by Ang II in DCT increased the activity of the WNK4-SPAK/OSR1-NCC axis associated with the development of hypertension." (PMID 39857434, 2025). "Another study conducted in Malaysia involving 320 volunteers classified based on hypertension and normotensive conditions showed that TT genotype/T allele of the WNK4 gene resulted in a close relationship between hypertension and T2DM11." (PMID 36646819, 2023). "Initial attention was focused on these enzymes as regulators of blood pressure because mutations of two family members, WNK1 and WNK4, caused pseudohypoaldosteronism type II, a heritable form of hypertension." (PMID 36212467, 2022). "Mutation of this glutamine to glutamate in WNK4 is associated with hypertension and at physiological pH would remove the hydrogen bond donor for this intramolecular interaction." (PMID 35179207, 2022). "Mutations in WNK1 and WNK4 genes caused a Mendelian form of hypertension, Familial Hyperkalemic Hypertension (FHHt) also known as pseudohypoaldosteronism type 2 or Gordon’s syndrome." (PMID 33066544, 2020). "Gain-of-function mutations of WNK1 and WNK4 cause a mendelian hypertension and hyperkalemic disease." (PMID 32131390, 2020). "Gain-of-function of WNK1 and WNK4 caused by gene mutation leads to an autosomal-dominant disease pseudohypoaldosteronism type 2 (PHA2) featured by hypertension, hyperkalemia and hyperchloremic metabolic acidosis." (PMID 32131390, 2020). "Firstly, thiazide diuretics correct both hyperkalaemia and hypertension in patients with Gordon syndrome, including in patients who have WNK4 mutations and animal models with mutant Wnk4." (PMID 31795491, 2019). "We targeted Ala589Ser polymorphism of WNK4 as a candidate gene in hypertension to specify potential association affecting high blood pressure determination." (PMID 27314050, 2016). "According to Wilson and colleagues, mutations in WNK4 can cause some autosomal dominant Mendelian trait contributing to hypertension." (PMID 27314050, 2016). "Significant association of Ala589Ser polymorphism, WNK4 gene, and hypertension has been specified in Malaysian genotype." (PMID 27314050, 2016). "Argumentative consequences have lately arisen on the association of specific single nucleotide polymorphisms of WNK4 gene and essential hypertension (EHT)." (PMID 27314050, 2016). "This study emerged under the circumstances in order to elucidate the role of WNK4 gene polymorphisms in development of hypertension." (PMID 25266424, 2014). "Though we tried our best to control the potential bias from statistical aspect and estimated the association between WNK4 gene polymorphisms and hypertension as reliable as possible, some limitations of our study should be concerned." (PMID 25266424, 2014). "Consistently, the results of this meta-analysis confirmed the association of WNK4 gene variation with the susceptibility of hypertension." (PMID 25266424, 2014). "Since then, a series of animal experiments and epidemiologic studies concentrated on the association between WNK1 and WNK4 gene mutations and hypertension or blood pressure regulation." (PMID 25266424, 2014). "Further well-designed studies with larger sample size are required to elucidate the association of WNK4 gene multiple polymorphisms with hypertension risk." (PMID 25266424, 2014). "The present study suggested a significant relationship between WNK4 G1155942T polymorphism and hypertension in the allelic genetic model and dominant genetic model." (PMID 25266424, 2014). "There are four mammalian WNK family members, and WNK1 and WNK4 genes are linked to a hereditary form of human hypertension known as Pseudohypoaldosteronism type II (PHAII)." (PMID 23383144, 2013). "Some mutations in human WNK1 or WNK4 are associated with Pseudohypoaldosteronism type II, a form of hypertension." (PMID 23383144, 2013).
Hypertension (continued). "Transgenic and knockin mice expressingthese WNK4 mutations display marked hypertension, but the molecular mechanism by which these mutations disruptWNK4 function to cause hypertension is unclear." (PMID 23387299, 2013). "It is known that genetic mutations in the kinase WNK1 and WNK4 cause a disease featuring hypertension and hyperkalemia and the etiology appears to be related to regulation of NKCC and KCC." (PMID 23537040, 2013). "There are four mammalian WNK family members, and positional cloning has identified two of them, WNK1 and WNK4, as genes linked to a hereditary form of human hypertension known as Pseudohypoaldosteronism type II (PHAII)." (PMID 23383144, 2013). "Interestingly, the epidemiological data indicated that high blood pressure caused by WNK4 mutation is delayed in females compared to males." (PMID 39968083, 2025). "Aside from hyperkalaemia and metabolic acidosis, a mild hyperchloraemia and calcium leak can be seen (especially with WNK4 mutations), which can present as hypercalciuria, hypocalcaemia, low bone mineral density, and renal stones, and these findings can precede hypertension." (PMID 31795491, 2019). "Most notably, mutations in WNK4 cause the Mendelian disease Familial hyperkalemia and hypertension (FHHt), which results in a hyperactive NCC and clinically presents with hypercalciuria and low bone mineral density in addition to hypertension, hyperkalemia, and metabolic acidosis." (PMID 31496133, 2019). "Moreover, the results of this case control study confirmed the association of WNK4 gene variation with the susceptibility of hypertension." (PMID 27314050, 2016). "Moreover, WNK4 C6749T polymorphism was also found to be significantly associated with hypertension susceptibility under allele contrast, dominant genetic model and homozygous genetic model." (PMID 25266424, 2014). "In conclusion, this meta-analysis suggested that WNK4 G1155942T and C6749T gene polymorphisms may contribute to the susceptibility and development of hypertension." (PMID 25266424, 2014). "Therefore, 16 independent case-control studies were finally collected in this meta-analysis to evaluate the relationship between the WNK4 gene polymorphisms and hypertension including 6089 cases and 4881 controls." (PMID 25266424, 2014). "Therefore, in order to estimate the relationship between WNK4 gene polymorphisms and hypertension, especially G1155942T, G1156666A, T1155547C, and C6749T, we performed this meta-analysis." (PMID 25266424, 2014). "In conclusion, the current meta-analysis suggested that the G1155942T and C6749T polymorphisms of WNK4 gene may increase the susceptibility of hypertension." (PMID 25266424, 2014). "The association of WNK4 C6749T polymorphism with hypertension was found to be significant in allele contrast (OR = 2.04, 95% CI/: 1.60–2.59, P<0.01), dominant genetic model (OR = 2.04, 95% CI: 1.59–2.62, P<0.01) and homozygous genetic model (OR = 5.01, 95% CI: 1.29–19.54, P = 0.02)." (PMID 25266424, 2014). "In addition, no meta-analysis has yet been conducted to assess the relationship between WNK4 polymorphisms and hypertension risk as we know." (PMID 25266424, 2014). "Although these features are also thought to be caused by WNK1 or WNK4 mutations, the details of how these pathologies occur are unknown except for hypertension." (PMID 23383144, 2013). "Activation of the WNK4-SPAK/OSR1-NCC signaling axis is one of the master signal pathways responsible for hypertension." (PMID 39857434, 2025). "Although there are limitations in the development of therapeutics for hypertension, the possibility of a therapeutic strategy targeting the regulatory pathway, WNK4-SPAK/OSR1, as a master activator of NCC is promising." (PMID 39857434, 2025). "Previous studies affirmed that the hypertension in WNK4 mutant mice resulted from increased WNK4 activity." (PMID 39968083, 2025).
Hypertension (continued). "Mice carrying the PHAII mutated WNK4 transgene (TgWnk4PHAII mice), which results in higher WNK4 activity, not only exhibit hypertension and hyperkalemia, but also acidosis." (PMID 38195948, 2024). "In db/db diabetes mouse, PKC phosphorylates KLHL3 on Ser433 and results in WNK4 accumulation, accelerating hypertension in T1DM." (PMID 37006236, 2023). "The pathological role of WNKs in electrolyte imbalance and hypertension was discovered by the identification of disease-associated variants in the WNK1 and WNK4 genes." (PMID 37845702, 2023). "Treatment of the patient with thiazide diuretics corrected both hyperkalemia and hypertension, which provides evidence of increased signaling through the WNK4-SPAK/OSR1-NCC axis in FHHt." (PMID 37845702, 2023). "Mutations in KLHL3 or WNK4 discovered in FHHt patients disrupt the interaction between KLHL3 and WNK4, leading to insufficient degradation of WNK4 and, ultimately, hypertension." (PMID 35327608, 2022). "WNK4 has been reported to directly inhibit NCC and is a strong inhibitor of NCC, which deletion causes overactivity of NCC and thus hypertension." (PMID 36305246, 2022). "Mutations of WNK1 and WNK4 cause Gordon syndrome (pseudohypoaldosteronism type 2, PHA 2) accompanied by hypertension, elevated serum potassium, and acidosis." (PMID 36305246, 2022). "Hypertension and hyperkalemia in pseudohypoaldosteronism type-2 (PHA2) patients with WNK1 and WNK4 mutations lead to the understanding of roles of WNK kinases in ion homeostasis." (PMID 32131390, 2020). "Gene mutations in WNK1 and WNK4 result in over-activation of the WNK-SPAK/OSR1 pathway, therefore increased phosphorylation and activation of NCC occurs in the kidney, resulting in hypertension." (PMID 33066544, 2020). "Mutations in WNK1, WNK4, KLHL3, and CUL3 all result in the accumulation of WNK-kinase 4 and subsequent hypertension, hyperkalaemia, and metabolic acidosis." (PMID 31795491, 2019). "This indicates that ClC-K2/b contributes to the low-K+-induced hypertension via the WNK4-SPAK-NCC cascade." (PMID 29326302, 2018). "Patients with WNK4 mutations leading to excessive NCC expression in distal tubules suffer from volume expansion and hypertension." (PMID 24797667, 2014). "Cumulative meta-analysis of the relationship between WNK4 SNPs and hypertension were performed according to the year of publication." (PMID 25266424, 2014). "The present study provides further insights into how Kelch-like adaptor proteins recognize their substrates and provides a structural basis for how mutations in WNK4 and KLHL3 lead to hypertension." (PMID 24641320, 2014). "Disruption of Spak-Ncc cascade can efficiently correct hypertension and hyperkalemia in the Wnk4-PHA II mouse model." (PMID 24039833, 2013). "We targeted conserved noncoding regions in hypertension candidate genes WNK1 and WNK4 to polymorphism screening in order to identify functional variants potentially contributing to BP determination." (PMID 21520334, 2011). "We also found that WNK4 (its mutations lead to hypertension) expression, but not WNK1, was significantly increased in CLDN7−/− CD cell lines as well as in primary CLDN7−/− CD cells, suggesting that the expression of WNK4 was modulated by CLDN7." (PMID 31382627, 2019). "With-no-lysine (K) Kinase-4 (WNK4) consisted of unique serine and threonine protein kinases, genetically associated with an autosomal dominant form of hypertension." (PMID 27314050, 2016). "The results of our meta-analysis indicate that WNK4 might be a potential target for hypertension therapeutic intervention." (PMID 25266424, 2014). "The relationship between with-no-lysine [K] kinase 4 (WNK4) gene polymorphisms and hypertension has been widely investigated, However, the studies yielded contradictory results." (PMID 25266424, 2014). "Whereas, biological evidence was absent to support the association between WNK4 C115547T and G1156666A polymorphisms and risk of hypertension." (PMID 25266424, 2014).
Hypertension (continued). "The central role of the kinase WNK4 in modulation of NCC activity was discovered when mutations on Wnk genes were responsible for around 20% of the clinical manifestations of pseudohypoaldosteronism type II (PHAII), characterized by hyperkalemia and hypertension, due to hyperactivity of NCC." (PMID 36790288, 2023). "Thus, patients with heterozygous CUL3 pathogenic variants are more likely to develop severe hyperkalemia, metabolic acidosis, hypertension, and growth impairment at an early stage than individuals carrying recessive KLHL3, dominant KLHL3, WNK4, or WNK1 pathogenic variants." (PMID 37895227, 2023). "In humans, gain-of-function mutations in WNK1 and WNK4 result in Familial Hyperkalemia and Hypertension (FHHt; sometimes referred to as pseudohypoaldosteronism type II (PHAII) or Gordon Syndrome), a monogenic form of secondary hypertension characterized by hypertension and hyperkalemia." (PMID 35895103, 2022). "Mutation in WNK1 and WNK4 genes could cause disturbances in the homeostasis of K+, salts, and pH level, whereas a mutation in AGT genes present on chromosome 1 results in an imbalance of angiotensinogen production, ultimately leading to hypertension." (PMID 30875817, 2019). "Although the statistical bias could not be avoided completely, this study indicated that WNK4 gene G1155942T and C6749T polymorphisms were associated with an increased risk of hypertension." (PMID 25266424, 2014). "However, no meta-analysis examining the association of WNK4 gene mutations with the risk of hypertension existed." (PMID 25266424, 2014). "Several genes including WNK1, WNK4, Bp1, Bp2, AGT, and ACE were reported to be involved in hypertension." (PMID 30875817, 2019). "The contribution of an impaired sympathoinhibitory ARN reflex to sex- and age-dependent hypertension in an NCC-dependent manner, via an impaired WNK1/WNK4 dynamic, suggests this pathway as a mechanism-based target for the treatment of age-dependent hypertension." (PMID 38976131, 2024). "The lysine kinases 1 and 4 (WNK1 and WNK4), identified as hyperactive in the hereditary disease pseudohypoaldosteronism type 2, are responsible for activation of NCC and consequent hypokalemia and hypertension." (PMID 36790288, 2023). "Subjects carrying missense mutations in the WNK1 conserved acidic motif have a clear electrolyte phenotype without hypertension, especially in comparison with those who have similar nucleotide variations in a similar protein motif of WNK4." (PMID 37895227, 2023). "Although WNK4[D564A] knockinmice that develop hypertension have been described, unfortunately no direct quantitative comparisonof the relative expression levels of the wild-type and mutant WNK4 in any tissue waspresented in that study." (PMID 23387299, 2013).